TNF (tumor necrosis factor)
Diseases named in the same sentence as TNF in open-access papers (continued):
Sharing a sentence is not in itself a finding about the gene and the disease.
tumor (continued). "In patients with aggressive breast cancers, these pDC exhibit suppressed IFN-α secretion and are able to sustain CD4+ Treg expansion, and the suppression of IFN-α production by pDC has been attributed to tumor-derived TGFβ and TNFα mediated-signaling in these cells." (PMID 23874338, 2013). "High expression of PI3K, p-Akt, IL-6, TNFα and VEGF were significantly associated with the higher histological grade, and high expression of PI3K, p-Akt and IL-6 were significantly associated with tumor recurrence." (PMID 23688241, 2013). "Since IKKβ has been identified as an Hsp90 client protein, we hypothesize that combined treatments with 17-DMAG and TNF may lead to a promising anti-tumor effects if 17-DMAG can decrease the survival signaling properties of TNF." (PMID 23635099, 2013). "Thus, tumor-derived TNF-α appears to play a minor role in the down-regulation of nepmucin expression." (PMID 24376728, 2013). "Similarly, the presence of TNF-α enhanced tumor development after the two-step carcinogenesis with either DMBA/TPA or with DMBA, followed by tumor promotion with okadaic acid." (PMID 24403255, 2013). "Comparison of TNF-α and IL-6 levels in the serum of tumor-bearing mice." (PMID 24225772, 2013). "Interestingly, the tumor spheroid (3-D) conditioned media contained significantly higher concentrations of both IL-6 and TNF-alpha than that of healthy donor plasma." (PMID 23372803, 2013). "After looking at other cytokines not directly associated with tumor progression (e.g., TNFα and IL-5), we observed that the production in untreated MM is almost overlapping with that scored by control PBMC (data not shown)." (PMID 24489445, 2013). "TNFα, IL-6 and IL-17 are important links between chronic inflammation and tumor development." (PMID 23937962, 2013). "However, it is almost impossible to expect that TNF-α or TRAIL can accumulate to a concentration high enough to kill tumor cells in vivo, let alone determine the relationship of TNF-α level in patients and prognosis." (PMID 23451095, 2013). "In fact, TNF- and TNFR1-deficient mice developed fewer tumours after exposure to a skin carcinogen." (PMID 23852022, 2013). "TNFα may act as a tumor promoter by regulating a cascade of cytokines, chemokines, adhesions, matrix metalloproteinases (MMPs) and pro-angiogenic activities." (PMID 24260500, 2013). "To further confirm the modifying effects of TNF-α promoter variant on risk of HPV16-associated SCCOP, we assessed the association of the combined risk genotypes with HPV16-positive SCCOP patients based on tumor HPV16 status instead of HPV16 serology." (PMID 23870134, 2013). "In addition, a number of microphages secreting bFGF, tumor necrosis factor (TNF), and VEGF were shown to be associated with tumor angiogenesis." (PMID 23983401, 2013). "TNF-α is produced by monocytes and macrophages, and can inhibit the proliferation of tumor cells." (PMID 24028754, 2013). "TNF-α may be involved in carcinogenesis through induction of proliferation, invasion, and metastasis because it may have both tumor-necrotic and tumor-promoting activities." (PMID 23870134, 2013). "Other strategies have been pursed to target TNF to the tumor." (PMID 24062984, 2013). "It has been reported that celastrol could suppress NFκB activation and led to potentiate tumor cells toward tumor necrosis factor induced apoptosis." (PMID 23442930, 2013). "Further, target antigens used to deliver TNF in these scFv-TNF fusion proteins are often not tumor specific but tumor associated or overexpressed, such as the Epidermal Growth Factor Receptor (EGFR) or Her2." (PMID 23840967, 2013). "MC-released TNF-α, IL-1, and IL-6 inhibit tumor growth and angiogenesis in melanoma." (PMID 23577028, 2013).
tumor (continued). "IOI-42, as a novel small molecule inhibitor of hPEBP4, has been reported to sensitize tumor cells to TNF-α and TRAIL-mediated apoptosis, suggesting that hPEBP4 interference with a specific pharmacologic inhibitor is capable of sensitizing cancer cells when used in combination with other drugs." (PMID 23451095, 2013). "Moreover, although TNFα was cytotoxic to some of the tumor cells, its cooperativity with estrogen and EGF has led to selection of tumors cells that have gained high metastasizing abilities in vivo, in an animal model system." (PMID 24369447, 2013). "Targeting TNF to the tumor vessels enhances tumor permeability to chemotherapeutic agents." (PMID 24062984, 2013). "Besides, several tumor cell types such as ovarian and breast cancers were found to constitutively express TNF-α, which leads to constitutive activation of NF-κB signaling, thereby rendering the tumors cell survival highly addicted to this factor." (PMID 23573150, 2013). "Overall, our results suggest that some of the cancer cells that were stimulated by TNFα + Estrogen + EGF partly succumbed to the cytotoxic effects of TNFα and others migrated out of the initial tumor inoculum, giving rise to smaller primary tumors than those generated by control cells." (PMID 24369447, 2013). "Furthermore, TNF-α and IL-1β supported tumor immune escape in vitro, by inducing the expression of TNF-related Apoptosis-inducing Ligand (TRAIL) on the surface of liver cancer cells, which in turn promoted apoptosis of activated T cells." (PMID 23533994, 2013). "The tumour levels of TNF-α were quite lower when compared to those of the liver." (PMID 23408945, 2013). "However, they are crucial for cytolytic effector functions of CTLs, especially their ability to produce IFN-γ and TNF-α, to release perforin-containing cytolytic granules, to induce FasL and to kill tumour cells." (PMID 23922331, 2013). "In addition, its significant anti-tumor effect was confirmed by injection of recombinant TNF-α into tumor-bearing mice." (PMID 23573150, 2013). "TNFerade is a novel means, using gene transfer, of selective delivery of TNF-α to tumor cells." (PMID 23533319, 2013). "In anti-inflammatory studies, three general categories of inflammatory inducers are considered including, i) gram-negative bacterial cell wall lipopolysaccharide (LPS); ii) proinflammatory cytokines such as tumor necrosis factors (TNF-α); and iii) the tumor promoter agent TPA." (PMID 23408313, 2013). "Although TNFα has been considered as an anticancer agent, it is currently recognized that chronically elevated TNFα in tissues may promote tumor growth, invasion and metastasis." (PMID 23431386, 2013). "Obviously, the critical balance between TGF-β and TNF-α might have a key role on tumor transformation." (PMID 24015203, 2013). "TNF-α, which is an extraordinarily pleiotropic cytokine, could be an endogenous tumor promoter in some tumor types." (PMID 24066693, 2013). "Moreover, a luciferase plasmid driven by an NFκB-responsive element was stably transfected into tumor cells, and the resultant reporter cell line was then evaluated in the hollow fiber model after treatment of the host mice with either LPS or TNF-α." (PMID 23301056, 2013). "When 4T1 cells were inoculated into the mammary pad of interleukin -1 receptor (IL-1R)-deficient mice, the levels of cytokines, including IL-6, TNFα and MCP-1, in the tumor tissue were significantly reduced and both tumor progression and lung metastasis were reduced." (PMID 23527025, 2013). "It will be interesting to see if hemocytes also associate with tumors in this paradigm and whether similar pro-tumor and anti-tumor roles for Egr/TNF signaling can be elucidated." (PMID 24392358, 2013). "The decision of a cell to become quiescent or proliferating is thought to depend on both nutrient and oxygen availability and on the presence of tumor necrosis factor, a substance produced by necrotic cells that somehow inhibits the further growth of the tumor." (PMID 23508803, 2013).
tumor (continued). "The macrophages differentiated from BMC of orlistat-administered mice showed characteristic features of M1 macrophage phenotype confirmed by expression of CD11c, TLR-2, generation of reactive oxygen species, phagocytosis, tumor cell cytotoxicity, production of IL-1,TNF-α and nitric oxide." (PMID 24349275, 2013). "However, TNF-α can also have pathological consequences such as promoting the growth of some tumor cell types." (PMID 23533448, 2013). "We further examined whether KSG-002 affects the viability of either tumor cells or macrophages in TNFα-confluent tumor microenvironment." (PMID 23818931, 2013). "Therefore, we further investigated the level of tumor-specific immune response by conducting IFN-γ or TNF-α ELISPOT assay." (PMID 23844018, 2013). "We further determined whether tumor cell cytotoxicity of all SE supernatants could be attenuated by the addition of anti-TNF-α to L-NMMA." (PMID 23964349, 2013). "The production of pro-inflammatory cytokines, IL-1β, IL-6, and TNFα, all of which facilitate tumor growth, in the tumor microenvironment might be due to STAT3 hyperactivation in both the tumor and immune cells." (PMID 23730621, 2013). "Additionally, the therapeutic mechanism of this antitumor immunity in mice inoculated with RdB/IL23/p35 is associated with the generation and infiltration of IFN-γ- and TNF-α-co-secreting T cells in tumor microenvironment." (PMID 23844018, 2013). "Overall, while TNFα had the ability to exert cytotoxic effects that may reduce tumor growth, it cooperated with the two other arms of the tumor microenvironment and eventually turned into a metastasis-promoting entity." (PMID 24369447, 2013). "We found that the combined risk genotypes were also significantly associated with tumor HPV16-positive SCCOP, indicating that the combined risk genotypes of TNF-α SNPs may contribute to HPV16-assoctaed SCCOP." (PMID 23870134, 2013). "Moreover, to follow on the cell-remodeling, EMT, and metastatic/invasive properties acquired by tumor cells that were exposed to the combined stimulation by TNFα + Estrogen + EGF, we determined the migratory functions of the cells." (PMID 24369447, 2013). "However, four tumor-derived cytokines (IL-6, IL-8, TNF-α, and IFN-γ) were found time-dependently induced in the SiHaparental group." (PMID 24325392, 2013). "It has been proposed that high expression of TNF- α might be involved in tumor growth and spread through influencing tissue remodeling and stromal development." (PMID 23326309, 2013). "Several different models have been suggested for the basic growth rate of in vitro tumor spheroids, and several different mechanisms are possible by which tumor necrosis factor might halt growth." (PMID 23508803, 2013). "TNF-α, which has a positive correlation in the stroma and a negative correlation in the epithelium when associated to the intensity of the inflammatory infiltrate in cases of OSCC, appears to favor tumor progression following transformation." (PMID 23833665, 2013). "Nguyen and coworkers observed that activation of STAT3 signaling in tumor cells or in inflammatory immune cells modulates secretion of various inflammatory factors such as IL6 and TNFα that act as an immunosuppressors, and increase the probability of survival of tumor cells." (PMID 24199193, 2013). "We hypothesized and confirmed in vitro that tumor cell sensitivity to TNF-α and the subsequent NT5E expression was PPARγ-dependent." (PMID 24133572, 2013). "Furthermore, TNF-α increases vascular permeability 7 and reduces the tumor's interstitial fluid pressure 8 facilitating the penetration of antitumor agents at the tumor site." (PMID 24156020, 2013). "Therefore, in more advanced stages of the research we focused on the effects of the joint stimulation by TNFα + Estrogen + EGF on functional tumor-promoting readouts, including tumor growth and metastasis formation." (PMID 24369447, 2013).
tumor (continued). "In addition, we also noted that increased expression of TNF-α and cleaved caspase-8 was associated with the RBM5 overexpression in tumor tissues." (PMID 23721095, 2013). "Since nude mice have defective cellular immune, extremely few lymphocytes were seen in tumor tissue of control group of our experiment, while lymphocytes could be seen in both CD group and TNF-α group; TIC group showed most frequent lymphocytes." (PMID 23593411, 2013). "Additionally, TNFR1-deficiency attenuated experimental lung and liver metastasis in a mouse model and treatment of tumour cells or mice with TNF increased the metastatic activity of transplanted malignant cells." (PMID 23852022, 2013). "Efficient inhibition of tumor growth was recently shown to involve not only defined cell death and clearance mechanisms by CD8+ cytotoxic T lymphocytes and natural killer cells, but also the induction of tumor cell senescence by interferon-γ and TNF producing CD4+ T-helper 1 cells." (PMID 23987103, 2013). "The opposing roles of TNFα in cancer may be due to interactions that the cytokine has with other procancerous elements that reside at the tumor milieu." (PMID 24369447, 2013). "In vitro experiment has demonstrated that TNF-α could accelerate the gathering of chemotherapeutic agents in certain tumor cells and help reach the half inhibitory concentration in a short period of time." (PMID 23593411, 2013). "Therefore, the small tumor growth endowed following TNFα + Estrogen + EGF stimulation provided a false benefit, because it has led to selection of cells expressing a higher metastasizing potential." (PMID 24369447, 2013). "Despite its dual role, identifying the pathways regulating UV-induced TNFα release is of importance because if it is an anti-tumor agent then pharmacological enhancers of the p38 MAPK pathway may increase its expression in targeted tumors." (PMID 23965971, 2013). "We observed a significant elevation in the IFN-γ and TNF-α production of tumor-specific immune cells in groups administrated with RdB/IL23/p35 compared with RdB/IL12-administrated groups (P<0.01), confirming the results obtained by IFN-γ and TNF-α ELISPOT assay." (PMID 23844018, 2013). "The EBV-Ex uptake was detected only in monocyte/macrophage (Mo/Mf) and EBV-miRNAs effects were potent on Mo/Mf in inducing CD69, IL-10, and TNF, suggesting the possibility that EBV-miRNAs might polarise Mo/Mf into tumour-associated Mf." (PMID 26082317, 2013). "It is possible that irritation and TNF-α induction are downstream effects of protein phosphatase inhibition, although this appears unlikely in view of tumour promotion by other irritant materials, such as TPA, lyngbyatoxin and palytoxin, which have not been reported to inhibit protein phosphatases." (PMID 23381142, 2013). "Consequently, NK cells can still kill tumor targets through FasL/Fas interaction and/or TNFα-mediated cytotoxicity." (PMID 23667543, 2013). "However, these cells, although intended to help promote tumor clearing, can inadvertently aid in the promotion and expansion of tumor growth through secreted cytokines including TNF-α and IL-6." (PMID 24244348, 2013). "However, an increasing body of evidence puts TNFα on the stake as a key tumor-promoting factor that has harmful impacts on the malignancy cascade." (PMID 24369447, 2013). "To further confirm whether RdB/IL23/p35 mediates up-regulation of antitumor cytokines (IFN-γ and TNF-α) secreted by tumor-specific immune cells, we co-cultured splenocytes with irradiated B16-F10 or NIH3T3 for 3 days in the presence of recombinant human IL-2." (PMID 23844018, 2013). "Notably, SEG induced robust activation of NO/TNFα-dependent tumor cell apoptosis comparable to the other egcSEs and SEA despite TNF-α and IFN-γ levels that were 2 and 8 fold lower, respectively, than the other egcSEs and SEA." (PMID 23964349, 2013).
tumor (continued). "In the anti-tumour immunity which is predominantly cellular, T cells are the main immune cells that can be cytotoxic directly, or indirectly through the secretion of cytokines TNF-α, IFN-γ." (PMID 22978453, 2012). "This enhancement might produce some cytokinetic products, such as tumor necrosis factor, interleukins, interferons etc. which in turn may be responsible in destroying tumor cells." (PMID 23691484, 2012). "Finally TNF-α enhances tumour angiogenesis through different angiogenic factors such as IL-8 and VEGF, and also is a critical regulator of VEGF and jagged-1 expression via a JNK- and AP-1- dependent pathway." (PMID 23905066, 2012). "The second therapeutic strategy we propose is targeted-delivery of TNF to the tumour site." (PMID 23326670, 2012). "Indeed, tumour-reactive CD4+ T helper 1 cells (Th1) produce several cytokines (such as IFN-fγ, TNF-α and IL-2) essential for the induction of cell-mediated immunity against tumours." (PMID 23284752, 2012). "Therefore, the tumor cells themselves, and some cytokines, including IL17, TNF-α generated from liver infiltrated T-cells in the tumor environment all contributed to early HCC recurrence." (PMID 23227158, 2012). "Studies are ongoing to further clarify the biological impact of MTDH overexpression on DLBCL tumor cells, in which we investigated gain-of-function through MTDH upregulation induced by TNF-α and loss-of-function through MTDH knockdown by small interfering RNA in DLBCL cells." (PMID 22768080, 2012). "If the D1(A12) was unable to inhibit TNF-α shedding by ADAM17 deep in the tumour this pharmacokinetic feature could also explain the discrepancy between the in vitro and in vivo studies, as the cells in vitro would all be exposed to the antibody." (PMID 22792380, 2012). "The effects of adoptively transferred Cl-IB-MECA-treated CD8+T cells in vivo could, therefore, be due to a locally released cytokines, such as TNF-α, in the tumor microenvironment." (PMID 23028986, 2012). "In the course of these studies, we asked whether in the context of ILP, tumour cell killing could also play a role in addition to the vascular effect of TNF-α." (PMID 22719951, 2012). "There is evidence that chronic synthesis of low amounts of TNF within a tumour microenvironment promotes tumour growth and favours angiogenesis, whereas higher doses can induce necrosis of tumour cells, stimulate antitumour immunity, and trigger vascular collapse." (PMID 23326670, 2012). "In our study, we considered the influnce of inflammatory microenvironment on MSCs, and used IFNγ and TNFα stimulating MSCs to imitate the tumor inflammatory microenvironment, and then took the conditioned medium to treat different HCC cells, which was different from the conditions mentioned aboved." (PMID 22952657, 2012). "In order to determine the antitumour effects of TNF-α, an ex vivo tumour culture assay, recapitulating conditions that might occur in vivo during ILP, was performed." (PMID 22719951, 2012). "However, in addition to its well-defined role in apoptosis, TNF-α can critically affect the immune response at tumor sites." (PMID 23028986, 2012). "Defects in the TNF cytotoxicity pathway or activation of TNF-dependent NF-κB survival genes may, in contrast, contribute to taxane resistance in tumor cells." (PMID 22225778, 2012). "In addition to this wide variation in sensitivity of tumour cells, the therapeutic value of TNF-α in the treatment of cancer has been limited by toxicity at high doses." (PMID 22719951, 2012). "TNF-alpha, another key inflammatory cytokines, plays a central role in the tumour progression." (PMID 22963460, 2012). "TNF-α produced by tumours can act as an endogenous tumour promoter." (PMID 23905066, 2012). "Moreover, M1 macrophages have been shown to regulate EMT at the invasive front through paracrine TNF-α signaling and Snail stabilization, linking tumor inflammation to EMT and metastasis." (PMID 22273460, 2012).